CD44 (CD44 molecule (IN blood group))
Diseases named in the same sentence as CD44 in open-access papers (continued):
Sharing a sentence is not in itself a finding about the gene and the disease.
cancer (continued). "Furthermore, we detected enhanced levels of at least one cancer stem cell (CSC) marker among CD133, CD24, and CD44 in 59% of the samples analyzed (n = 14)." (PMID 28700115, 2017). "Taken together, our collected data strongly suggests that the co-localization of Myc and CD44 is not a cell line-specific phenomenon and Myc-expressing cells are enriched with cancer stem cells." (PMID 28427212, 2017). "Besides being a biocompatible and biodegradable polymer, HA has been shown to promote angiogenesis in various types of tumors, and HA receptors such as CD44 and RHAMM are highly overexpressed in cancer cells." (PMID 28181831, 2017). "Finally, we observed that basal expression of CSC-related genes (ID1, CD44, HES7 and TCF3) significantly correlate with ONC201 efficacy in >1000 cancer cell lines and combining the expression of multiple genes leads to a stronger overall prediction." (PMID 28767654, 2017). "As shown by many authors, the correlation of CD44 expression and the prognosis in various cancers is not uniform." (PMID 28659655, 2017). "In addition, these cells were also positive for the cancer stem cell markers, Aldehyde Dehydrogenase 1 (ALDH1A1) and CD44 suggesting that these cells display some characteristics of stem-ness." (PMID 29187162, 2017). "Experimental results showed that culturing cancer cells on chitosan increased cell motility, drug resistance, quiescent population, self-renewal capacity, and the expression levels of stemness and CSC marker genes, such as OCT4, NANOG, CD133, CD44, and EpCAM." (PMID 28367998, 2017). "An antibody, conjugated to Cy5 fluorophores, raised against EpCAM that is expressed on the cell membranes of most carcinomas, and an antibody conjugated to FITC fluorophores prepared against CD44, another cell membrane protein expressed on tumors of epithelial origin, were used." (PMID 28085924, 2017). "4MU, like HAS2, has been shown to reduce CD44 and RHAMM receptor expression in cancer cells." (PMID 27595989, 2016). "Gal-1 may also mediate attachment of cancer cells to the ECM and endothelial cells through binding to CD44." (PMID 27686492, 2016). "The exact mechanism by which this SNP modulates cancer risk has not yet been elucidated; however, its location in the 3′UTR suggests that it alters the binding of miRNA contributing CD44 deregulation." (PMID 27521214, 2016). "We speculated that drug-resistant cells may have cancer stem cell-like characteristics, which can be detected by the CSC surface markers CD44 and CD133." (PMID 27738333, 2016). "The therapeutic effects of targeting other stem cell markers, including Sox-2 or CD44 were reported using bulk cancer cells, although the CSC fractions were not studied in isolation." (PMID 26973599, 2016). "Moreover, the genetic ablation of NAG-1 suppressed the expression of cancer stemness biomarkers including SOX2, OCT4, and CD44." (PMID 27708225, 2016). "EMT also generated cells with characteristics of cancer stem cells (CSC) and expression of CD44." (PMID 27525003, 2016). "The subpopulation of CD44+/CD24−/low cells has been shown to exhibit cancer stem-like properties, and these cell surface markers have been used as functional markers for sorting cancer stem cells from parental cell lines." (PMID 27313840, 2016). "To assess the involvement of cell-surface gC1qR in lamellipodia formation, we investigated the gC1qR and CD44 localization of lamellipodia in various non-permeabilized cancer cells using mAb 3D9." (PMID 27363031, 2016). "To further investigate whether overexpression of CD44 and CD24 plays roles in reprogramming differentiated cancer cells to CSC-like phenotype, we ectopically expressed CD44 and CD24 in NPC parental cells." (PMID 27521216, 2016). "In PDAC, cells expressing surface CD24, CD44 and ESA were identified as putative cancer stem cells." (PMID 27203385, 2016). "Unlike other cancers, the absence of CD44 expression indicates aggressiveness and poor clinical outcome in NB." (PMID 27686492, 2016).
cancer (continued). "In line with this hypothesis, cancer cells expressing SOX2 showed an increased expression of the stem cell markers CD24 and CD44." (PMID 27411517, 2016). "This seems to indicate that CD44 links MMP-14 and the actin cytoskeleton in invasive cancer cells." (PMID 27590006, 2016). "It has been widely reported that CD24-/CD44+ are the two cell surface markers used for isolating tumorigenic CSC from non-tumorigenic cancer cells." (PMID 27842518, 2016). "Several former researches showed that the Wnt, PI3K/AKT, and SHH/Gli1 pathways may be activated in CD44 positive and/or CD133 positive cancer cells." (PMID 26769843, 2016). "None of the eligible studies for CD44 polymorphism rs11821102 indicate a positive correlation with statistical power associated with cancer; yet pooled analysis demonstrated that the minor allele of rs11821102 polymorphism might be related to a decreased cancer risk in Chinese." (PMID 28000766, 2016). "Finally, we analyzed the CD44+ and CD24−/low populations in mouse-cell-depleted cancer cells isolated from obtained from vehicle-, metformin- or MFB (250 mg/kg)-treated xenograft tumors." (PMID 27223262, 2016). "GSCs lacking A3AR exhibited common properties of Cancer Stem Cells forming neurospheres clusters expressing the Stem Cells markers (CD44, CD133 and Nestin)." (PMID 27634913, 2016). "Of these, CD44 and RHAMM have been extensively studied in cancer biology." (PMID 27595989, 2016). "Moreover, R182 cells showed enhanced levels of cancer stemness biomarkers such as OCT4, SOX2, CD44, and CD133, compared with the marginal expression of these factors in A2780 cells." (PMID 27708225, 2016). "After 24 h of incubation with the samples, cancer cell viability was reduced at least 3-fold while CD44-negative control cell lines remained minimally affected." (PMID 27182458, 2015). "After confirming ADAM10 downregulation by western blot analysis, blots were reprobed with c-Myc, cyclin D1 as well as CD44, all of which showed reduction in ADAM10 depleted cells, indicating that ADAM10 regulates catenin-dependent intracellular signaling in the cancer cells." (PMID 26440150, 2015). "Interestingly, it has been reported that Akt is activated in a specific subset of cancer stem cells that express CD133, CD44 and CD24." (PMID 26485768, 2015). "As is the case with the SFDM sphere-induced tumors, these tumors were positive for CD44, vimentin, laminin and diffusely positive for CD31 and CD34 staining, suggesting that the anti-miR-17 cancer sphere cells were able to recapitulate both renal and endothelial cell types of RCC." (PMID 25011053, 2015). "In this study, CD133+high/CD44+high DU-145 and PC-3 CSCs were able to form spheroids in non-adherent culture, suggesting the presence of cancer stemlike cells within these cells." (PMID 26485709, 2015). "These cells are CD44+CD24−/low cancer cells and they establish tumors in recipient animals when as few as one hundred cells are transplanted, whereas tens of thousands of cancer cells with a different marker set fail to form tumors." (PMID 26712794, 2015). "Interestingly, Snail, CD44, G3BP2, and YAP1 are targets of Wnt5A, a gene involved in invasion and metastasis of many cancers, that is regulated by NF-κB signaling pathway." (PMID 25738332, 2015). "There is increasing evidence that CD44 is involved in cancer development, but it has not been reported to interact with TrkA or participate in its downstream signaling." (PMID 25840418, 2015). "In the present study, we investigated whether HA/CD44 plays an important role in the TGF-β1-induced EGF signaling transactivation and EMT in cancer cells." (PMID 26005723, 2015). "The development of fluorescence-activated cell sorting (FACS), together with the establishment of specific cell surface markers, permitted the subsequent identification of CSCs in solid tumours: breast (CD44+CD24-/low), prostate and ovarian (CD44+), brain and lung (CD133+) cancers, and others." (PMID 25708542, 2015).
cancer (continued). "In contrast, there are no spheres formed in non-cancer stem-like CD44-/CD24- cells after X-ray or carbon ion beam, either alone or in combination with CDDP." (PMID 26338199, 2015). "Cancer stem cells are molecularly characterized based on the expression of various cell surface receptors including integrin a6 (CD49f), integrin b1 (CD29), hyaluronan receptor (CD44), and the stem cell self-renewal transcription factors NANOG, OCT4, and SOX2." (PMID 26005638, 2015). "Indeed, following CD44 knockdown in MDA-MB-435s, we found that cancer cells tended to accumulate in the S- and G2/M-phases of the cell cycle and decreased the proportion of cells in the G1-phase, alluding to a role for CD44 in cell cycle control." (PMID 25605020, 2015). "As the majority of high passage UM-HMC-3B cells stain highly for CD44, we next questioned whether ALDH could be used as a single marker for this aggressive cancer stem cell phenotype." (PMID 26449187, 2015). "Importantly, we were able to validate these findings using low-passage cancer cell lines (UM18 and UM59) derived from human primary PDA samples, where silencing of ATDC significantly inhibited CD44, Snail1, and Zeb1 expression." (PMID 25593307, 2015). "In the area of lower differentiation status where cancer cells are crowded by the active proliferation and have increased nuclear/cytoplasmic ratio without keratinization, we clearly observed a Brm+, CD44+, MET+, and CAV1+ phenotype in almost all cases." (PMID 25673149, 2015). "Moreover, ectopic expression of Snail or Twist or exposure to TGF-β induces EMT in immortalized human mammary epithelial cells (HMLE) and increases the formation of tumor spheres and CD44+/ CD24− cells, also known as cancer stem-like cells (CSCs)." (PMID 26462028, 2015). "In this report, we demonstrate for the first time that NGF induces TrkA/CD44 interaction independent of TrkA phosphorylation in cancer cells." (PMID 25840418, 2015). "CD44 has been studied for three decades, but no consensus opinion on cancer progression has been reached until now." (PMID 26666511, 2015). "In our study we found only six familial BCs with CD44 positive/CD24 negative phenotype that defines cancer stem cells in BC." (PMID 26312763, 2015). "Moreover, NANK cells differed from their original cancer as well, such as that CD133 and CD44 were expressed in original cancer but rather weakly in NANK." (PMID 26284927, 2015). "These associations exist and activate signaling cascades without direct binding of CD44 to its ligand, highlighting the importance of CD44 as a co-receptor and emphasizing its importance and potential in targeted cancer therapy." (PMID 25954275, 2015). "Through unsupervised clustering in stage II cancers, we identified two cluster groups that are broadly defined by inflammatory or immune-related factors (CD3, CD8, COX-2 and FOXP3) and stem-like factors (CD44, LGR5, SOX2, OCT4)." (PMID 25906747, 2015). "Importantly, BORIS-silencing led to down-regulation of hTERT, stem cell (NANOG, OCT4, SOX2 and BMI1) and cancer stem cell markers (ABCG2, CD44 and ALDH1) genes." (PMID 26185996, 2015). "Two CD44-positive cancer cells lines, HeLa and A549 cells, and two CD44-negative normal cell lines, Huvec and NIH-3T3 cells, were incubated with the samples to assess selectivity and cytotoxicity." (PMID 27182458, 2015). "Further, CD44 is used as a marker for cancer stem cell (CSC) detection in a variety of cancers without much research into the function of CD44 in stem cells beyond adhesion." (PMID 25954275, 2015). "Up- and down-regulated genes in all three putative CSCs (A549 CD166+/CD44+, A549 CD166+/EpCAM+, and H2170 CD166+/EpCAM+) were found to be involved in several biological cancer processes, including angiogenesis, apoptosis, anti-apoptosis, induction of apoptosis, cell death, and cell migration." (PMID 25881239, 2015).
cancer (continued). "Although CD147 and CD44 showed no increase in expression in carcinomas, they were more frequently expressed in MCT positive tumors, which is in accordance with their role as MCT chaperones." (PMID 26587828, 2015). "Post-translational events of this nature offer a novel (non-genomic) possibility to help explain the controversy that CD44 expression levels alone do not always correlate directly with prognosis in different cancers." (PMID 24512624, 2014). "This is contrary to other MFS data, which did not account for the CD44 isoforms but is confirmed by data from other cancer types." (PMID 24491153, 2014). "In the present study, we have isolated the CD24+/CD44+ population from HNSCC cell lines and determined whether this cell population has cancer stem cell properties by a variety of different approaches." (PMID 24612587, 2014). "In conclusion, Met expression, activation state, subcellular localization and also HGF co-receptors expression, such as CD44, have clinical relevance for novel targeted therapies in a cancer for which no effective treatment is currently available." (PMID 28548074, 2014). "CD44 has been studied for three decades, with hundreds of papers devoted to cancer research, but no consensus opinion on cancer progression has been reached until now." (PMID 24708709, 2014). "CD44 is a cell surface glycoprotein belonging to the chondroitin sulphate proteoglycan family (CSPG8) and acts as a necessary co-receptor for Met activation and signaling in several cancers and primary cells." (PMID 28548074, 2014). "Cancer stem cells (CSC), which express CD133, CD44, ATP-binding cassette sub-family G member 2 (ABCG2) and Aldehyde dehydrogenases (ALDH), are a subpopulation of tumor cells that display self-renewal and the ability to give rise to heterogeneous lineages of cancer cells." (PMID 25084809, 2014). "We recognize that GSC markers, including CD144 and CD44, are not sufficient to functionally characterize a cancer stem cell, therefore additional studies are needed to determine the role of HCMV in GSC biology in vivo." (PMID 25549333, 2014). "In addition, when we knocked down the STAT3 gene, CD44+ subpopulation was reduced, suggesting the pivotal role of STAT3 in the cancer stem cell transition in HER2 amplified environment." (PMID 24297508, 2014). "Pancreatic CSCs identified with the marker profile ESA+/CD44+/CD24+ have the ability to form spheres in nonadherent conditions which distinguishes them from non-cancer stem cells which lack this ability." (PMID 24647545, 2014). "While the EMT/MET genetic program has yet to be fully understood in cancer, recent studies showed that upregulation of two novel EMT key markers, CD44 and CD24, are necessary for entry into a mesenchymal-like state in highly drug resistant breast HER2 positive carcinoma." (PMID 24504051, 2014). "The expression of CD44 and CEA as markers of prognosis in several types of cancer is well known." (PMID 24699516, 2014). "Interestingly, we found that DDX3X induced increase of cancer cells accompanied by stem-like phenotypes such as upregulated expression of Sox2, ALDH, and CD44." (PMID 25343452, 2014). "Under these conditions, I3C treatment of 10AT-Her2 cells did not alter the expression of the cancer stem/progenitor cell-like marker proteins nucleostemin, CD44, CD24 and ALDH-1." (PMID 25209720, 2014). "The expressions of EpCAM, CD24, CD44, CD133, and CXCR4 antigens were membranous in carcinoma cells." (PMID 25240521, 2014). "Thus, we evaluated the significance of cancer stem cell markers, including CD133, CD44, and EpCAM, in CLC." (PMID 23192764, 2013).
cancer (continued). "GOD3-2C4 also binds different known Tn-positive proteins from different cancer cell lines, e.g. CD44 and mucins (data not shown)." (PMID 23637900, 2013). "In head and neck squamous cell carcinoma, a CD44+ population of cells possesses the properties of CSC, and aldehyde dehydrogenase 1 (ALDH1) activity has also been reported to identify cancer stem cells in a host of cancer types." (PMID 24376802, 2013). "Our study clearly showed that CD44 interacts with STAT3 then possibly transduces the signals through STAT3-hTERT pathway, which may activate Wnt signaling in the cancer stem cell population." (PMID 24386318, 2013). "Furthermore, the present study verified the expression of the cancer invasion-related genes, MMP-1, MMP-2, EGFR and COX-2, which were upregulated in the CD44+ GC cells, indicating a capacity to manipulate cancer invasion and even metastasis." (PMID 23833643, 2013). "Consistent with this prediction, increased expression of the cancer invasion-related genes matrix metalloproteinase (MMP)-1, MMP-2, epidermal growth factor receptor (EGFR) and cyclooxygenase 2 (COX-2) were detected in the CD44+ stem-like cells." (PMID 23833643, 2013). "HA-based micelles showed significantly higher cellular uptake by a CD44 overexpressed cancer cell line compared to a CD44 negative cell line, NIH3T3." (PMID 24300453, 2013). "We hypothesize the interactions between CD44, STAT3 and hTERT signaling pathways that occur in the human malignancies are deregulated in the cancer stem cells." (PMID 24386318, 2013). "Interestingly, some SUM cell lines express markers of some of cancer stem cell (CSC) populations namely, ALDH, CD44+, and CD24−." (PMID 23401782, 2013). "CD44, a cell surface glycoprotein that functions as a receptor for hyaluronic acid (HA), a component of the extracellular matrix (ECM), has been identified as a cancer stem cell marker in many cancer types, including breast, brain, prostate, and HNSCC." (PMID 24403253, 2013). "It is the PI3K-Pdk1 pathway, but not Akt or Erk what increases the survival of more stem-like cells with higher levels of the stem and cancer markers Sca-1, CD44 and Sox9, in absence of p38 activity." (PMID 24265727, 2013). "Cells with a CD44+/CD24- phenotype were detected in 40 out of 130 samples with an advantage of high grade tumors (II and III) and metastases among tubular, papillary and carcinomas in mixed tumors." (PMID 24119896, 2013). "Conversely, in carcinomas in mixed tumors, immunostaining for CD44 was seen on epithelial cells but not in well-differentiated mesenchymal tissue or in myoepithelial cells." (PMID 24119896, 2013). "Given that CD44 is the main stem cell marker for HNSCC, these results suggest that EGFR activation may be crucial for maintaining a cancer stem cell phenotype." (PMID 22384257, 2012). "In addition to meeting the requirements for lymphatic uptake and dissemination, HA’s primary receptors, CD44 and RHAMM, are overexpressed on most malignant cancer cells, including invasive breast cancer and melanomas." (PMID 24300232, 2012). "CD133, CD44, ESA and ALDH1 are widely considered as markers of cancer stem/progenitor-like cells." (PMID 22895640, 2012). "CD44 is a primary receptor for hyaluronan (HA), a major component of the extracellular matrix (ECM) and critical for cell signaling and cell-ECM interactions in cancer." (PMID 22870202, 2012). "Previous reports have shown that CD44 and CD147 are close partners in various cancers." (PMID 22870202, 2012). "A number of reports have demonstrated that CD44 is present in lipid rafts, but the role of lipid rafts in cancer cell adhesion and migration has not been elucidated." (PMID 22253629, 2012). "Previous studies suggested that downregulation of CD44 allowed BCSCs to differentiate into cancer non-BCSCs or normal cells in breast tissue." (PMID 22152097, 2011). "CD44, CD24, ESA, CD133, CXCR4 are the cancer stem cell marker for pancreatic cancer." (PMID 22082307, 2011).